ANKFY1 (ankyrin repeat and FYVE domain containing 1)
Description:
Proposed effector of Rab5. Binds to phosphatidylinositol 3-phosphate (PI[3]P). Involved in homotypic early endosome fusion and to a lesser extent in heterotypic fusion of clathrin-coated vesicles with early endosomes. Involved in macropinocytosis; the function is dependent on Rab5-GTP. Required for correct endosomal localization. Involved in the internalization and trafficking of activated tyrosine kinase receptors such as PDGFRB. Regulates the subcellular localization of the retromer complex in a EHD1-dependent manner. Involved in endosome-to-Golgi transport and biosynthetic transport to late endosomes and lysosomes indicative for a regulation of retromer complex-mediated retrograde transport. Required for podocyte migration.
Synonyms: Rank-5; ANKHZN; KIAA1255; ZFYVE14; BTBD23
Tractability: Antibody: UniProt places it where antibodies can reach, with high confidence. PROTAC: ubiquitination databases record sites on it; its protein half-life has been measured.
Gene: Protein-coding gene on chromosome 17 (4,163,821 to 4,263,995, reverse strand). Ensembl gene ENSG00000185722.
Subcellular location: Cytoplasm; Endosome membrane; Early endosome
Subcellular location (Human Protein Atlas): Endosomes
Pathways (Reactome):
Signal Transduction: RHOD GTPase cycle
Gene Ontology:
Molecular function: phosphatidylinositol phosphate binding; protein binding; small GTPase binding; metal ion binding
Biological process: endosomal transport; endosomal vesicle fusion; Golgi to lysosome transport; positive regulation of pinocytosis; retrograde transport, endosome to Golgi
Cellular component: cytoplasm; early endosome; endosome; endosome membrane; extracellular exosome; lysosomal membrane; macropinosome; membrane; retromer complex; cytosol
Genetic constraint (gnomAD): Loss-of-function variants: 46 observed, 126.9 expected, observed/expected ratio (o/e) 0.36, 90% interval 0.28 to 0.46. The upper end of that interval is the gene's LOEUF score, 0.46, which puts it in group 2 of 6, group 1 being the genes least tolerant of losing a copy. Missense variants: 1,211 observed, 1,521.1 expected, observed/expected ratio (o/e) 0.8, 90% interval 0.76 to 0.83. Synonymous variants: 551 observed, 611.82 expected, observed/expected ratio (o/e) 0.9, 90% interval 0.84 to 0.97.
Homologues: Orthologues: chimpanzee ANKFY1 (99% identical), macaque ANKFY1 (98% identical), mouse Ankfy1 (95% identical), pig ANKFY1 (95% identical), guinea pig ANKFY1 (95% identical), rat Ankfy1 (95% identical), dog ANKFY1 (93% identical), rabbit ANKFY1 (92% identical), tropical clawed frog ankfy1 (87% identical), zebrafish ankfy1 (84% identical), Drosophila melanogaster CG41099 (42% identical), Caenorhabditis elegans F22G12.4 (31% identical).
Diseases named in the same sentence as ANKFY1 in open-access papers:
ANKFY1 is named in the same sentence as 15 diseases in open-access papers, as found by Europe PMC text mining. Sharing a sentence is not in itself a finding about the gene and the disease. The quoted sentences say what the papers report.
Ataxia (3 papers, 2017 to 2025). Ataxia refers to impaired coordination of voluntary muscle movement. "Ankfy1/+ mutant mice show severe ataxia and a substantial loss of Purkinje cellsdue to increased apoptosis during a period of programmed cell death (PCD)." (PMID 28588446, 2017). "It is possible that Ankfy1 was dysregulated and altered levels of Ankfy1 led to ataxia in cases of this study." (PMID 33796010, 2021).
nephrotic syndrome (3 papers, 2020 to 2024). A collection of symptoms that include severe edema, proteinuria, and hypoalbuminemia; it is indicative of renal dysfunction. "Only one family with steroid-resistant nephrotic syndrome has been reported carrying a homozygous variant in ANKFY1 so far." (PMID 38915441, 2024). "Another study has identified a homozygous missense mutation in ANKFY1 to be a potential cause of nephrotic syndrome, a disease commonly comorbid with diabetes and cardiovascular disease." (PMID 36042491, 2022). "Examples include mutations in the genes GTPase activating protein and VPS9 domains 1 (GAPVD1) and ankyrin repeat and FYVE domain containing 1 (ANKFY1) which were identified to cause a recessive type of nephrotic syndrome by impairing nephrin trafficking." (PMID 32708597, 2020).
chronic kidney disease (1 paper, 2024). Impairment of the renal function secondary to chronic kidney damage persisting for three or more months. "ANKFY1 encodes a gene involved in endocytosis, disruption of which has been implicated in the pathophysiology of proteinuria in chronic kidney disease such as SRNS and Dent disease." (PMID 38915441, 2024).
osteoporosis (1 paper, 2025). A condition of reduced bone mass, with decreased cortical thickness and a decrease in the number and size of the trabeculae of cancellous bone (but normal chemical composition), resulting in increased fracture incidence. "Meanwhile, APS inhibited the expression of miR-760 and increased the expression of ankyrin repeat and FYVE domain-containing protein 1 (ANKFY1), ultimately promoting osteogenic maturation and growth of human BMSCs and providing a new therapeutic strategy for osteoporosis." (PMID 40766304, 2025).
spastic ataxia (1 paper, 2025). "Because of the specific expression of PCP2 in Purkinje cells, we postulated that ARHGDIB and PCP2 are the critical target proteins related to ANKFY1 deficiency-induced spastic ataxia." (PMID 40594855, 2025). "We also hypothesized that Rho-GTPase might be involved in spastic ataxia caused by ANKFY1 deficiency." (PMID 40594855, 2025). "This study aimed to explore the pathogenesis of abnormal ANKFY1-mediated spastic ataxia more precisely in the cerebellum through DIA-based proteomics and bioinformatics analyses." (PMID 40594855, 2025). "Our proteomic analysis of conditional Ankfy1 knockout mice may guide future research to help develop treatments for progressive spastic ataxia." (PMID 40594855, 2025).
neurodegenerative disease (1 paper, 2017). A disorder of the central nervous system characterized by gradual and progressive loss of neural tissue and neurologic function. "We propose that transgenic Ankfy1/+mice are a useful model for studying the pathogenesis of ARSACS and for exploring themolecular mechanisms involved in this neurodegenerative disease." (PMID 28588446, 2017).
ANKFY1 also shares sentences with these, for which no sentence is quoted: cancer (1 paper); cardiovascular disease (1); cerebellar ataxia (1); Dent disease (1); diabetes (1); Gliosis (1); HIV-1 infection (1); movement disorder (1); tumor (1).